VIM (vimentin)
Diseases named in the same sentence as VIM in open-access papers (continued):
Sharing a sentence is not in itself a finding about the gene and the disease.
squamous cell carcinoma (25 papers, 2006 to 2025). A carcinoma arising from squamous epithelial cells. "Immunohistochemical analysis usually demonstrates a “vimentin-only” phenotype, excluding some other neoplasms such as sarcomatoid variants of squamous cell carcinoma, spindle cell carcinoma, vascular tumors, or synovial sarcoma—showing negative to their markers." (PMID 32102165, 2020). "The conventional squamous cell carcinoma has an epithelial phenotype, being positive to E-cadherin and beta-catenin, opposite to the signet ring component, which has a mesenchymal phenotype (diffuse expression of vimentin, beta-catenin with nuclear translocation and partially loss of E-cadherin)." (PMID 38256374, 2024). "In this regard, in some squamous cell carcinoma cell lines, the EMT-specific phenotype was associated with the loss of E-cadherin and induction of vimentin and MMP-2." (PMID 40724562, 2025). "Among 188 patients with curatively resected NSCLC, 127 adenocarcinomas and 61 squamous cell carcinomas were stained for PD–L1 and vimentin expression." (PMID 31546725, 2019). "A further large-scale study is needed to evaluate the roles of EDIL3 and vimentin in squamous cell carcinoma." (PMID 28819306, 2017). "These tumors co-express cytokeratin and vimentin but generally they are rare and display a heterogeneous histology, mixed with adeno- or squamous cell carcinoma parts, making the analysis of the EMT impact on e.g. overall survival difficult." (PMID 26421614, 2015). "In this study, we seeked to define the prognostic potential of cytokeratin and vimentin expression patterns in squamous cell carcinomas (SCC's) of the oral cavity." (PMID 16412231, 2006). "Additionally, vimentin has minimal expression in cancer tissue, which explains the genesis and progression of squamous cell carcinoma of the lung when it is CSE-induced." (PMID 36056339, 2022). "Compared to A549 cells treated with serum-derived exosomes from ADK WT, squamous cell carcinoma, and healthy donors, A549 cells treated with exosomes from patients with an EGFR mutation showed a significant increase of vimentin and a slight decrease of E-cadherin, canonical markers of EMT." (PMID 35954442, 2022). "The expression profile of vimentin was further divided based on differentiation of tumour as 5 (31.25%) into well differentiated (G1), 8 (40%) in moderately differentiated (G2), and 11 (45.83) in poorly differentiated squamous cell carcinoma." (PMID 27190522, 2016). "A previous study demonstrated that Akt overexpression induces EMT by upregulating the mesenchymal cell-specific markers, including Vimentin and Fibronectin, and downregulating epithelial cell-specific markers, including E-cadherin, in squamous cell carcinoma lines." (PMID 27323412, 2016). "Tumors developed under the effects of prenatal exposure contained basal cell carcinoma (BCC) and squamous cell carcinoma (SCC) types, with increased levels of PCNA, MMP 9, and Vimentin at 18 weeks." (PMID 38519574, 2024). "Different squamous cell carcinoma cell lines exhibited cell type dependent differential expression of TFAP2A and Vimentin (VIM) genes that corroborates inter cell line heterogeneity." (PMID 34490084, 2021). "The number of patients with squamous cell carcinoma was relatively small and the incidence of EDIL3+ or Vimentin+ was low." (PMID 28819306, 2017). "In squamous cell carcinoma patients, EDIL3 expression was significantly correlated with low e-cadherin expression (P = 0.021) and high vimentin expression (P = 0.002)." (PMID 28819306, 2017). "Less differentiated squamous cell carcinoma specifically expresses vimentin as well as CK and CK5/6 but not CK20, CK7, and neuroendocrine markers (including CD56, CgA, and Syn)." (PMID 41245381, 2025). "Vimentin positive tumor cells have been detected among squamous cell carcinomas; although, high epithelial vimentin has not been correlated with tumor grade." (PMID 25852822, 2015).
fibrosis (24 papers, 2012 to 2025). the formation of excess fibrous connective tissue in an organ or tissue in a reparative or reactive process. "OPN and VIM also exhibited higher diagnostic performance at distinguishing earlier stages of fibrosis (controls and F0 fibrosis) compared to HA and P3NP, with TIMP1." (PMID 30559459, 2018). "The presence of colonic mucosal fibrosis, identified using MT staining and IHC for vimentin, was correlated with failure to attain clinical remission and death because of GI disease." (PMID 37052621, 2023). "We also analyzed the expression of Neat1 and vimentin, a cardiac fibrosis marker, by immunofluorescence staining and found that Neat1 and vimentin were both upregulated in the areas with cardiac fibrosis." (PMID 34980170, 2022). "HPSCs are like hepatic stellate cells, which are important effector cells in hepatic fibrosis, and stain positive for vimentin, desmin, and α-SMA." (PMID 36332889, 2022). "Vimentin knockout (KO) or inhibition of vimentin has been shown to decrease collagen production, reduce lung injury, and protect the lung from developing fibrosis." (PMID 34634931, 2021). "Next, to validate that WFA was also effective in targeting soluble vimentin in Tenon's capsule in the GFS model of fibrosis, we exploited a localized subconjunctival method for WFA delivery as described in Methods." (PMID 23667686, 2013). "Expression of genes critical for cardiac fibrosis, such as αSMA, fibronectin, vimentin and MMP9 was significantly increased in old αMHC-Cre/Foxm1fl/fl hearts compared to age-matched controls." (PMID 23144938, 2012). "Compared to the no-fibrosis specimens, we found that staining of N-cadherin, α-SMA and vimentin was very strong in fibrosis specimens." (PMID 22294131, 2012). "Notably, the decrease in TGF-β and vimentin expression underscores potential dysregulation of protective mechanisms, possibly contributing to cardiac fibrosis and dysfunction." (PMID 40426976, 2025). "Moreover, the quantification of total collagen deposition, α-SMA, collagen I, collagen III and vimentin positive area per small airway revealed a significant increase of those fibrosis markers in CS-exposed mice as compared to air-exposed animals." (PMID 36646720, 2023). "The results of the qRT-PCR analysis confirmed further increases in the renal fibrosis markers vimentin and FSP-1 in the SAMP1-50wk mice, and that the expression of the glomerulosclerosis marker podocin was decreased in the SAMP1-20wk mice, SAMP1-30wk mice, 40-wk mice, and SAMP1-50wk mice." (PMID 35646947, 2022). "CRS mice showed a significant increase of circulatory and renal FGF23 protein levels, as well as an upregulation of p-GSK, active-β-catenin, TGF-β, collagen I and vimentin, a downregulation of renal Klotho expression and induction of cardiorenal dysfunction and cardiorenal fibrosis." (PMID 33460402, 2021). "We overexpressed miR-486-5p in MRC-5 cells, a cell line commonly used in fibrosis research, and observed a decrease in the expression of fibrosis genes, including Fn, α-SMA, vimentin, COL1A1, and COL3A1." (PMID 40692863, 2025). "The reduced airway fibrosis was further confirmed by immunofluorescence staining with α-SMA and vimentin." (PMID 36776398, 2022). "The increased airway fibrosis was further confirmed by means of immunofluorescence staining with α-SMA and vimentin." (PMID 36776398, 2022). "In order to evaluate the effect of Shenkang injection on UUO induced fibrosis, we analyzed the deposition of several ECMs, including collagen I, collagen III, and vimentin." (PMID 35721120, 2022). "In the absence of available single-cell RNA-seq data from donors with CF, we further confirmed the presence of both vimentin-positive and vimentin-negative α-cell sub-populations in donors with chronic pancreatitis characterised by established fibrosis." (PMID 39836539, 2025).
fibrosis (continued). "Compared with sham rats, 5/6NX rats showed significantly increased levels of SCr, BUN, and HA, as well as increased fibrosis area, glomerular sclerosis index, and fibrotic marker levels (COL1A1, VIM, and ACTA2), suggesting that the 5/6NX rat model was effective." (PMID 32854194, 2020).
fibrosarcoma (23 papers, 2011 to 2026). A malignant mesenchymal fibroblastic neoplasm affecting the soft tissue and bone. "CARMIL2 has been shown to provide a functional link between vimentin intermediate filaments and membrane-associated actin networks during lamellipodia formation, cell migration and invadopodia-mediated matrix degradation in fibrosarcoma cells." (PMID 28112205, 2017). "Histologically, the mass showed heterogenicity with immunohistochemistry (IHC) reactivity to vimentin, suggesting a diagnosis of fibrosarcoma of mesenchymal origin." (PMID 41594385, 2026). "Histopathological evaluation demonstrated a high-grade spindle cell tumor, initially interpreted as fibrosarcoma, showing diffuse vimentin positivity, a high Ki-67 proliferation index (35%-40%), and CD34 negativity." (PMID 41867924, 2026). "With the expression of vimentin and smooth muscle actin, fibrosarcoma can represent myofibroblastic differentiation." (PMID 40297646, 2025). "High-grade fibrosarcoma with Vimentin, Ki-67, and Caldesmon positive was diagnosed by immunochemistry." (PMID 40297646, 2025). "In line with a fibrosarcoma histology, several pinnal tumors were positive for vimentin, but this staining was often heterogeneous and about half of the tumors was essentially negative for vimentin." (PMID 35468745, 2022). "In fibrosarcoma cells CARMIL2 provides the molecular link between vimentin intermediate filaments and actin, thereby playing a role in cell polarity, lamellipodial assembly, and the creation of protrusions that allow cellular migration." (PMID 29479355, 2018). "Consistent with the immunophenotypic profile of low-grade malignant fibrosarcoma, only Vimentin is expressed in immunohistochemistry; SMA may show positive expression in instances of myofibroblastic differentiation; Desmin, CK, EMA, and CD34 were non-reactive." (PMID 39968290, 2024). "Using the Spearman correlation index, we observed, as expected, that RHOB expression negatively correlated with the hypoxia-induced gene signature in lung, breast and fibrosarcoma tumors, while VIM and ITGB2 expression were generally positively correlated in all three cancer patient cohorts." (PMID 35681731, 2022). "The positive staining of vimentin demonstrates the mesenchymal origin of fibrosarcoma." (PMID 29262667, 2017). "In fibrosarcoma, vimentin, is often the only positively stained marker." (PMID 29262667, 2017). "The main finding in the necropsy was an abomasal neoplasia with two metastases in the mesenterium which was positive for vimentin, but negative for smooth muscle actin and c-kit using immunohistochemistry, indicating a fibrosarcoma that might have contributed to gastrointestinal blood loss." (PMID 35573404, 2022). "Immunohistochemistry plays a crucial role in this differentiation, as fibrosarcoma typically expresses vimentin but not cytokeratins or smooth muscle markers." (PMID 41552272, 2026). "Histopathology showed low-grade fibrosarcoma; immunohistochemistry was positive for Vimentin and SMA, focally CD34, and negative for S100, Desmin, and Myogenin, with low Ki-67 (<3 %)." (PMID 41045685, 2025). "Fibrosarcoma usually expresses vimentin but is negative for S-100, desmin, and cytokeratin by immunohistochemistry." (PMID 40297646, 2025). "Fibrosarcoma cells express only vimentin and are negative for S-100, GFAP and neurogenic markers." (PMID 24396458, 2014). "These infantile fibrosarcomas were diffusely and robustly positive for Trk (100%), S100 protein (50%, 3/6 cases), nestin, CD10 (80%, 4/5 cases), and vimentin (100%), but negative for CD34, SMA, desmin, myogenin, and CD56." (PMID 32957984, 2020).
renal carcinoma (23 papers, 2006 to 2025). A carcinoma arising from the epithelium of the renal parenchyma or the renal pelvis. "Although the initial assumption was that this lesion was a metastasis from the renal carcinoma, immunohistochemical analysis positive for the neuroendocrine markers and vimentin, classified the pancreatic lesion as a clear cell pancreatic neuroendocrine tumor." (PMID 38619811, 2024). "The results represented that knockdown RBM47 reduced e-cadherin and facilitated snail and vimentin in renal cancer cells while RBM47 overexpression achieved the opposite results." (PMID 37962768, 2023). "In renal cancer cell lines, lentiviral PD-L1 knockdown led to low expression levels of Vimentin and higher levels of E-cadherin." (PMID 33138288, 2020). "TNF‐α induces EMT in renal cancer via repressing the E‐cadherin expression and enhancing Vimentin and MMP‐9 expressions." (PMID 33159487, 2020). "Core pluripotency stem cell master regulators (OCT4, SOX2 and NANOG) along with epithelial–mesenchymal transition (EMT) markers (Snail, Slug, vimentin and N-cadherin) were induced in human prostate, breast, lung, bladder, colorectal, and renal cancer cells." (PMID 30742096, 2019). "Vimentin has already been established as an immunohistochemistry marker to distinguish clear cell and papillary from both normal renal tissue and other renal cancer types." (PMID 30863721, 2019). "In addition, MLN4924 prevented the migration of renal cancer cells by up-regulating E-cadherin and inhibiting Vimentin." (PMID 36983561, 2023). "Mechanically, RBM47 could directly modify RNA stability of e-cadherin, but indirectly regulate snail, vimentin in renal cancer cells." (PMID 37962768, 2023). "Furthermore, a recent study showed that the treatment of renal cancer cells with recombinant HMGB1 induced vimentin/α-SMA expression and phenotypic change." (PMID 28727734, 2017). "In addition, Ki-67 can be used in combination with other markers such as MCM-2, survivin, B7-H1, geminin, carbonic anhydrase, IX, gelsolin, MIB-1, and phosphorylated S6 protein, and the interaction between white (pS6) and vimentin affects the prognosis of renal cancer." (PMID 35741311, 2022). "Immunohistochemically, this type of renal cancer exhibits the following characteristics: PAX+, Vimentin+, CK7–, CA IX–, CD10+, and TFE3+." (PMID 39851801, 2025). "Among different subgroups in renal cancer scRNAseq data, significant correlations between EMP1/COL3A1 and four EMT genes (VIM, SNAI2, TWIST1, and CTNNB1) were found in c9 fibroblasts." (PMID 38187400, 2023). "Then we examined the expression of mesenchymal markers in renal cancer cells after LGK974 treatment and the protein expression of N-cadherin, vimentin, and snail." (PMID 32104684, 2020). "In order to confirm the function of PIK3R1 in renal cancer cells, we analyzed the expression of ECAD, NCAD, VIM, SNAIL, and TWIST in normal renal cell (HK2) and RCC cell lines (786-O, A498, A704, and ACHN) with RT-PCR." (PMID 25757764, 2015). "The same results were verified in renal cancer tissues, with a positive correlation between RBM47 and CDH1(e-cadherin), a negative correlation between RBM47 and TGF-β, snail, vimentin by qRT-PCR, and western blot (WB)." (PMID 37962768, 2023). "A positive staining for cytokeratin as well as for vimentin and CD10 in the absence of staining for thyroglobulin, calcitonin and TTF1, observed in smears from both lobes of the thyroid, favored the hypothesis of metastasis from a renal carcinoma." (PMID 17067398, 2006).
sarcoidosis (23 papers, 2017 to 2025). Sarcoidosis is a multisystemic disorder of unknown cause characterized by the formation of immune granulomas in involved organs. "Vimentin, another prominent self-antigen implicated in sarcoidosis, is an intermediate filament protein upregulated in response to cellular stress, injury, and inflammation." (PMID 41197661, 2025). "A separate study has also identified vimentin as a component of the Kveim reagent, previously used for diagnostic purposes due to its ability to specifically induce granulomatous responses in sarcoidosis patients." (PMID 30038611, 2018). "Interestingly, anti-vimentin antibody has been previously proved to be associated with sarcoidosis." (PMID 36264970, 2022). "We found that genes associated with this pathway were significantly upregulated in vimentin-induced sarcoidosis compared to saline controls (VIM-ISO vs SAL, NES=1.92)." (PMID 41476976, 2025). "Our analysis also revealed valuable insights, indicating that pathways related to lipid metabolism and atherosclerosis were activated in the vimentin model, aligning well with findings from human sarcoidosis patient datasets." (PMID 41476976, 2025). "In many studies, autoantibodies to VIM and its modifications have been found in patients with sarcoidosis." (PMID 39765749, 2024). "Vimentin has been identified as one of the most likely endogenous antigens involved in the pathogenesis of sarcoidosis." (PMID 39598118, 2024). "Recent studies have demonstrated the formation of antibodies to vimentin in patients with sarcoidosis." (PMID 39598118, 2024). "Elevated levels of antibodies have been obtained in sarcoidosis patients to modify citrullinated vimentin." (PMID 39598118, 2024). "Other researchers have shown the formation of IgG and IgA antibodies against vimentin in the bronchoalveolar lavage fluid (BALF) of patients with sarcoidosis." (PMID 39598118, 2024). "Autoantibodies to vimentin and its modifications have been found in various studies in patients with sarcoidosis." (PMID 37109576, 2023). "Initially, the authors demonstrated that patients with sarcoidosis showed significantly (p = 0.0024) higher anti-vimentin IgG levels than controls and a greater prevalence of anti-vimentin IgG positivity (24/48: 50 vs.1/13: 7.6%, respectively; p = 0.0091)." (PMID 36148452, 2022). "According to the different studies, vimentin is a possible autoantigen that activates both cell and humoral autoimmune response in patients with sarcoidosis." (PMID 36010289, 2022). "Another hint about a possible pathogenetic role of vimentin in sarcoidosis arises from a recent study that investigated the systemic immune response to vimentin and its capacity to induce granuloma formation in a murine model of pulmonary sarcoidosis." (PMID 36148452, 2022). "There is no clinical observation-based evidence for intracellular pathogen inside the sarcoidosis granuloma, yet few studies have demonstrated the plausible presence of dormant mycobacterium in vimentin-positive antigen-presenting cells." (PMID 35573702, 2022). "As a first observation, the authors found that BALF titers of anti-vimentin antibodies (AVAs) were higher in patients with sarcoidosis than in healthy controls." (PMID 36148452, 2022). "IgG ant-vimentin was also higher in pulmonary-only sarcoidosis vs normal controls and extra-pulmonary sarcoidosis." (PMID 36264970, 2022). "There is a need to further characterize the antibody response to vimentin in relation to its possible involvement in pathogenicity of sarcoidosis and other lung disorders." (PMID 36010289, 2022). "In sarcoidosis patients, human leukocyte antigen DR type (HLA-DR)-bound peptides of vimentin were obtained in the bronchoalveolar lavage (BAL)." (PMID 34540380, 2021). "Vimentin is a possible autoantigen proposed as the culprit of the granulomatous inflammation seen in sarcoidosis." (PMID 33036432, 2020).